ENSG00000276087 (novel transcript)
Gene: Protein-coding gene on chromosome 2 (24,124,366 to 24,190,436, forward strand). Ensembl gene ENSG00000276087.
Genetic constraint (gnomAD): Missense variants: 113 observed, 128.65 expected, observed/expected ratio (o/e) 0.88, 90% interval 0.75 to 1.03. Synonymous variants: 35 observed, 44.39 expected, observed/expected ratio (o/e) 0.79, 90% interval 0.6 to 1.04.